PPARG (peroxisome proliferator activated receptor gamma)
Diseases named in the same sentence as PPARG in open-access papers (continued):
Sharing a sentence is not in itself a finding about the gene and the disease.
Granuloma (7 papers, 2013 to 2021). A compact, organized collection of mature mononuclear phagocytes, which may be but is not necessarily accompanied by accessory features such as necrosis. "Our previous studies demonstrated that PPARγ deficiency exacerbates granuloma formation in the MWCNT murine granuloma model." (PMID 33072094, 2020). "Secondly, we investigated the effect of pre-existing PPARγ deficiency on MWCNT-elicited granulomas by utilizing macrophage-specific PPARγ KO mice." (PMID 23343389, 2013). "In the MWCNT-instilled Mmp12 KO, increased PPARγ expression coincided with this granuloma resolution." (PMID 34681679, 2021). "Further studies with macrophage-specific Pparγ knock out (KO) mice revealed enhanced granulomatous disease as evidenced by increased granuloma size and incidence." (PMID 33072094, 2020). "With MMP12 upregulation (C57/Bl6), persistent PPARγ decrease and IFNγ increase results in granuloma persistence." (PMID 33072094, 2020). "Application of the MWCNT granuloma model will be a useful tool to explore the potential interactions of Twist1 with the transcription factors, NF-κB and PPARγ in subsequent studies of pulmonary granulomatous disease." (PMID 24322444, 2013). "Cytokines elevated by MWCNT exposure in PPARγ KO mice included osteopontin, which was found in granuloma tissue, BAL cells and fluids." (PMID 23343389, 2013). "Histologic comparison of wild-type C57Bl/6 and PPARγ KO lung tissues was carried out using a simplified scoring system taking into account size and frequency of granulomas." (PMID 23343389, 2013). "PPARγ KO mice also demonstrated elevated pro-inflammatory cytokine expression in lung tissue, laser-microdissected lung granulomas, and BAL cells/fluids, at 60 days post MWCNT exposure." (PMID 23343389, 2013). "Based on these observations we hypothesized that PPARγ might play a role in the formation of MWCNT granulomas." (PMID 23343389, 2013). "Based on such observations we hypothesized that PPARγ expression would be repressed in alveolar macrophages from animals bearing granulomas induced by MWCNT instillation." (PMID 23343389, 2013). "Whereas in the absence of MMP12 (Mmp12 KO), PPARγ increases and IFNγ decreases, resulting in granuloma resolution." (PMID 33072094, 2020).
idiopathic pulmonary fibrosis (7 papers, 2019 to 2024). Idiopathic pulmonary fibrosis (IPF) is a nonneoplastic pulmonary disease that is characterized by the formation of scar tissue within the lungs in the absence of any known cause. "The dysregulation of PPARG methylation has been documented in idiopathic pulmonary fibrosis (IPF) patients." (PMID 39595621, 2024).
infarction (7 papers, 2014 to 2025). A localised pathological necrosis of tissue resulting from obstruction of the blood supply usually by a thrombus, an embolus, or vascular torsion. "Additionally, TFPI2 promotes M2 macrophage polarization via PPARγ activation and attenuates fibroblast activation, thereby facilitating myocardial repair post-infarction in diabetic models." (PMID 40361374, 2025). "Retinoid X receptor (RXR)/PPARγ agonists, including bexarotene and rosiglitazone, elevated the number of Ym1 positive neutrophils by inhibiting NF-κB transactivation, which was also associated with the attenuation of BBB leakage, infarction enlargement, and neurological deficits." (PMID 34248961, 2021). "These PPARγ agonists profoundly maintained the TJs and BBB integrity, improved infarction injury and neurological score." (PMID 34248961, 2021). "Combined administration of PPARγ agonist and ADRSCs activated M2-polarized macrophages with enhancement of APN paracrine effects and lead to better cardiac function in a rat infarction model." (PMID 30902059, 2019).
leprosy (7 papers, 2016 to 2024). Leprosy is a chronic infectious disease affecting primarily the skin and peripheral nervous system. "At 3p25.2, we identified a non-coding variant nearby PPARG and SYN2 that were both significantly down regulated in the lesion of leprosy patients." (PMID 27976721, 2016). "The SNP rs6807915 located between SYN2 and PPARG gene, which were significantly down regulated in the lesion of leprosy patients." (PMID 27976721, 2016). "Therefore, exploring the PPARγ -A2AR axis in leprosy may provide relevant information about this disease." (PMID 39005937, 2024). "A qPCR performed to evaluate pro- and anti-inflammatory related gene expression in skin lesions of leprosy patients revealed that pro-inflammatory genes STAT1, TNF, IFNG, IL15 and CSF2 are increased in PB cells, whereas anti-inflammatory MSR1 and PPARG genes are increased in MB cells." (PMID 34354699, 2021).
Lipedema (7 papers, 2020 to 2025). Disorder of adipose tissue characterized by symmetric and bilateral enlargement of the lower extremities due to abnormal deposition of subcutaneous fat often in obese women. "A key transcription factor in adipocyte differentiation, peroxisome proliferator activated receptor-γ (PPARG), showed a slight trend of increase in PC derived from lipedema thigh tissue compared to healthy thigh tissue (p = 0.086)." (PMID 35625899, 2022). "Although the literature presents conflicting reports on the direction of ERα control over PPARγ activity, it is clear that a regulatory relationship exists between the two proteins and it should remain an interest of lipedema research." (PMID 34769153, 2021). "Reduced ERß could result in excess fat accumulation seen in lipedema as greater PPARγ activity resulting in increased adipogenesis and TAG storage leading to exacerbated fat tissue accumulation." (PMID 34769153, 2021). "ZNF423 expression in preadipocytes is related to the activation of PPARG and directly to the maturation of adipocytes; thus, upregulation of ZNF423 is a potential mechanism by which estrogen promotes hyperproliferation in lipedema." (PMID 36551837, 2022). "However, the expression of PPARγ, a down-stream target of ZNF423, only slightly increased in lipedema thigh PC, compared to healthy controls." (PMID 35625899, 2022). "This is partly supported by data showing significant upregulation of various adipogenic genes, including PPARγ, CD36/fatty acid translocase, and the fatty acid binding protein-4 (FABP4) in in vitro differentiated lipedema adipocytes from non-obese donors compared to non-lipedema controls." (PMID 36675759, 2022).
lung squamous cell carcinoma (7 papers, 2020 to 2023). "Moreover, the enhanced expression of PPARγ was detected in squamous cell lung carcinoma that was associated with tumor size." (PMID 35922782, 2022). "So far, only a few studies explored the relationship between PPARG and lung squamous cell carcinomas (LSCC)." (PMID 32565768, 2020). "However, a few studies reported the specific relationship between PPARG and lung squamous cell carcinoma (LSCC)." (PMID 32565768, 2020). "The PPARγ agonist pioglitazone significantly influences EMT gene expression, promoting a more epithelial, and less mesenchymal, phenotype in a murine lung squamous cell carcinoma model." (PMID 37048080, 2023).
medulloblastoma (7 papers, 2012 to 2024). A malignant, invasive embryonal neoplasm arising from the cerebellum. "It was reported that exosomal microRNAs could induce tumour‐associated macrophages via PPARγ during tumour progression in SHH medulloblastoma." (PMID 38680032, 2024). "For example, let‐7i‐5p and miR‐221‐3p induces M2 polarization and promotes medulloblastoma development by downregulating peroxisome proliferator activated receptor gamma (PPARγ) after delivery to TAMs via exosomes." (PMID 39247621, 2024). "TAM-derived exosomes showed reduced levels of let-7i-5p and miR-221-3p, which are inversely correlated with PPARγ expression in medulloblastoma." (PMID 39327610, 2024). "PPARG upregulates HK2 in medulloblastoma, and an agonist of PPAR signalling increases the rate of glycolysis in CD8+ cells." (PMID 35886000, 2022). "This is also documented in the actively proliferating Shh-responsive CGNPs in the developing cerebellum, and PPARγ expression is strikingly elevated in Shh-driven medulloblastoma in vivo." (PMID 22407012, 2012). "Here, we demonstrate the existence of a novel mechanism connecting Shh signaling to the PPARγ transcriptional machinery in neural precursors and in Shh-driven medulloblastoma." (PMID 22407012, 2012). "Our data show that in primary cerebellar granule neural precursors (CGNPs), proposed medulloblastoma cells-of-origin, Shh stimulation elicits a marked induction of PPARγ alongside major glycolytic markers." (PMID 22407012, 2012). "These striking results suggest a therapeutic potential for PPARγ inhibition in treating Shh-driven medulloblastomas." (PMID 22407012, 2012). "Medulloblastoma-derived exosomes were found to have reduced levels of let-7i-5p and miR-221-3p, prompting the induction of M2 polarization in TAMs through the upregulation of PPARγ." (PMID 39327610, 2024). "In addition, agonists of PPARγ reduce tumor growth in xenografted LN-229 cells, however it should be noted that antagonism of PPARγ conversely reduces tumor growth in Sonic hedgehog-driven mouse models of medulloblastoma." (PMID 28491867, 2017). "In addition, this process is fully reversible with antagonizing PPARγ, an event that remarkably blunts tumor proliferation and extends survival of animals with medulloblastoma in vivo." (PMID 22407012, 2012). "Indeed, olomoucine treatment resulted in a striking reduction of PPARγ levels in the NeuroD2-SmoA1 medulloblastomas." (PMID 22407012, 2012). "We have shown that Shh-driven medulloblastomas and their proposed cells-of-origin, cerebellar granule neuron precursors (CGNPs), exhibit high levels of lipogenesis, and here we report that these tumors feature increased PPARγ." (PMID 22407012, 2012). "Indeed, our data implicate this E2F1-dependent glycolytic process as a systematic, distinctly cell-autonomous process that is mediated by PPARγ but triggered by Shh in medulloblastoma." (PMID 22407012, 2012). "Taken together, the results of our in vivo analysis and in vitro manipulation of E2F1 indicate that in Shh-associated mouse medulloblastomas and in proliferating CGNPs, glycolysis is elevated in an E2F1-dependent manner and its regulation functionally lie downstream of PPARγ." (PMID 22407012, 2012). "We next examined whether in medulloblastomas expression of PPARγ, like that of FASN, requires E2F1 activity." (PMID 22407012, 2012). "The requirement for E2F1 in Shh-regulated PPARγ dependent-glycolysis, as demonstrated, highlights its engagement in metabolic core fluxes and underscores the critical role for the Rb/E2F complex in metabolic reprogramming of medulloblastomas and their cells-of-origin." (PMID 22407012, 2012). "In this study, we show that in medulloblastoma and CGNPs, the Shh pathway is coupled—through E2F1—to the steroid receptor PPARγ and the control of glycolysis, a vital cellular process." (PMID 22407012, 2012).
medulloblastoma (continued). "This also reveals a dominant role of Shh in the etiology of glucose metabolism in medulloblastoma and underscores the function of the Shh → E2F1 → PPARγ axis in altering substrate utilization patterns in brain cancers in favor of tumor growth." (PMID 22407012, 2012). "Here, using immunostaining and blotting techniques in mouse NeuroD2-SmoA1 medulloblastomas, we detected very robust levels of PPARγ in the tumors as opposed to the adjacent non-tumor cerebellar tissues." (PMID 22407012, 2012). "Importantly, pharmacological blockade of PPARγ and/or Rb inactivation inhibits CGNP proliferation, drives medulloblastoma cell death and extends survival of medulloblastoma-bearing animals in vivo." (PMID 22407012, 2012).
nonalcoholic fatty liver (7 papers, 2010 to 2023). "Our mechanic studies indicated that L-theanine can regulate lipid metabolism of nonalcoholic fatty liver through activating Ca2+-CaMKKβ-AMPK signaling pathway, inhibit the expression of ACC1, FASN and PPARγ which were related to fatty acid synthesis." (PMID 35428314, 2022). "PPARγ, which may be regulated by SIRT1, is thought to be involved in the development of alcoholic and nonalcoholic fatty liver." (PMID 21087523, 2010).
ovarian tumour (7 papers, 2004 to 2022). "The present study was designed to investigate whether expression of COX-2 and PPARγ is associated with ovarian carcinogenesis and progression of ovarian tumours." (PMID 15266333, 2004). "We also demonstrate that PPARγ expression pattern alters in high-grade ovarian tumours, implicating an important role for PPARγ in the progression of ovarian malignancy." (PMID 15583697, 2005). "Western blot analyses showed significant elevation in the expression of immunoreactive PPARγ in grade 3 ovarian tumours compared with that of normal ovaries and benign ovarian tumours (P<0.01)." (PMID 15583697, 2005). "This study demonstrates the relative expression of PPARγ in normal ovaries and different pathological grades of ovarian tumours of serous, mucinous, endometrioid, clear cell and mixed subtypes." (PMID 15583697, 2005). "The expression of PPARγ in human ovarian tumour tissues was also evaluated by Western blot analyses." (PMID 15583697, 2005). "The expression of PPARγ in ovarian tumour tissues was significantly higher than in normal ovaries and benign ovarian tumours (P<0.01)." (PMID 15583697, 2005). "Western blotting analyses demonstrated significant enhancement in the expression of PPARγ in grade 3 ovarian tumours compared to benign ovarian tumours and normal ovaries." (PMID 15583697, 2005). "Weak to moderate expression of PPARγ by immunohistochemistry was observed in almost all ovarian tumours studied." (PMID 15583697, 2005). "Compared to benign and borderline tumours, the extent of staining was, however, significantly increased in grade 3 ovarian tumours, with immunoreactivity for PPARγ being mostly present in the nuclear region." (PMID 15583697, 2005). "An altered staining pattern of PPARγ was observed in high-grade ovarian tumours with PPARγ being mostly localized in the nuclei with little cytoplasmic immunoreactivity." (PMID 15583697, 2005). "We show that ovarian tumours express PPARγ and that expression is significantly higher in malignant tumours compared to benign tumours and normal ovaries." (PMID 15583697, 2005). "Also, the increased PPARγ expression was detected in malignant and high grade ovarian tumors indicating the involvement of PPARγ in ovarian tumor development." (PMID 35922782, 2022). "Our results suggest that PPARγ promotes survival for some ovarian tumor cells." (PMID 21781307, 2011). "Whether this increased exposure of ovarian tumour cells to the inflammatory cytokines result in the activation of PPARγ and subsequent cytoplasmic translocation to the nucleus is yet to be determined." (PMID 15583697, 2005). "We report for the first time that ovarian tumours express PPARγ." (PMID 15583697, 2005). "Overall, the immunoreactive PPARγ was present in all grades of ovarian tumours." (PMID 15583697, 2005). "PPARγ staining in ovarian tumours was mainly localised to the cytoplasm or nuclei of tumour cells." (PMID 15583697, 2005). "Hence, a balance of PPARβ and PPARγ expression and activation may be needed to regulate ovarian tumour differentiation and metastases." (PMID 18349831, 2008).
pancreatic ductal adenocarcinoma (7 papers, 2012 to 2023). An infiltrating adenocarcinoma that arises from the epithelial cells of the pancreas. "A previous study identified novel genes associated with poor prognosis in pancreatic ductal adenocarcinoma by carrying bioinformatics analysis on PKM and PPARG." (PMID 33942483, 2021).
Parkinson’s (7 papers, 2012 to 2023). "Interestingly, the nuclear receptor, peroxisome proliferator-activated receptor-gamma (PPARγ) has been recognized as a therapeutic target for various neurodegenerative disorders such as Alzheimer's (AD), Parkinson's (PD), and HD." (PMID 35553009, 2022).
peritonitis (7 papers, 2016 to 2022). Inflammation of the peritoneum (tissue that lines the abdominal wall and covers most of the organs in the abdomen). "The goal of our study was to determine the role of STAT6 in PPARγ activation to resolve acute sterile inflammation in a zymosan-induced peritonitis murine model, which has been widely used as a self-resolving model of acute inflammation." (PMID 33652833, 2021). "Here, we studied the role of STAT6 signaling in PPARγ activation and the resolution of acute sterile inflammation in a murine model of zymosan-induced peritonitis." (PMID 33652833, 2021). "We further investigated the effects of macrophage PPARγ on infection resolution in E. coli-initiated peritonitis." (PMID 33927725, 2021). "We also found that EPO-promoted inflammation resolution via PPARγ induction in macrophages, which is consistent with previous work demonstrating that PPARγ activation normalizes peritonitis resolution in CGD mice." (PMID 27397585, 2016). "In the present study, we examined whether inhibition of STAT6 phosphorylation by AS1517499, a STAT6-specific pharmacological inhibitor, affects PPARγ expression and activation during zymosan-induced peritonitis." (PMID 35327639, 2022). "Our results indicate that specifically targeting the STAT6/PPARγ signaling pathway might be a novel therapeutic approach for treating sterile inflammatory diseases, including peritonitis." (PMID 35327639, 2022). "Moreover, the administration of rhEPO significantly enhanced levels of macrophage PPARγ and myeloid EPOR deficiency strongly reduced levels of macrophage PPARγ during E. coli-induced peritonitis." (PMID 33927725, 2021). "Thus, in the present study, we investigated whether modulating STAT6 activity using a selective STAT6 inhibitor, AS1517499, influences the inflammatory response in zymosan-induced peritonitis by regulating PPARγ expression and activity." (PMID 35327639, 2022). "Here, in a model of zymosan-induced peritonitis, we demonstrated the critical role of STAT6 activation in the recovery and enhancement of PPARγ expression and activation in peritoneal macrophages." (PMID 33652833, 2021). "However, PPARγ upregulation in macrophages was significantly decreased in EPOR-MKO and CGD mice during zymA-induced peritonitis, indicating potential regulation by EPO signalling." (PMID 27397585, 2016). "During acute peritonitis, PPARγ agonist treatment increased macrophage phagocytosis of ANs in EPOR-MKO mice; however, EPO did not enhance this process during acute peritonitis in PPARγ-MKO mice, demonstrating the important contribution of PPARγ to mediating EPO-promoted efferocytosis." (PMID 27397585, 2016).
rectal cancer (7 papers, 2017 to 2024). A primary or metastatic malignant neoplasm that affects the rectum. "Similarly, other polymorphisms that are related to decreased risk of rectal cancer are in the methylenetetrahydrofolate reductase (MTHFR) gene (rs1801133) and the peroxisome proliferators-activated receptor gamma (PPARγ) gene (rs1801282)." (PMID 37444557, 2023). "• Positive feedback loop between PPARγ and ID3 enhances the radiosensitivity of rectal cancer cells." (PMID 37170184, 2023).
renal carcinoma (7 papers, 2009 to 2025). A carcinoma arising from the epithelium of the renal parenchyma or the renal pelvis. "A dispensable role of PPARγ in rosiglitazone-mediated sensitization of human renal cancer cells to TRAIL-induced apoptosis was also demonstrated using a dominant-negative mutant of PPARγ." (PMID 26492315, 2015). "In addition, PPARG signaling activation causes lipolysis mediated by FABP4 and inhibits lung and renal cancer cell growth." (PMID 36114448, 2022).